PRM2 (protamine 2)
Description:
Protamines substitute for histones in the chromatin of sperm during the haploid phase of spermatogenesis. They compact sperm DNA into a highly condensed, stable and inactive complex.
Synonyms: CT94.2
Tractability: No criterion of Open Targets' tractability assessment is met for any kind of drug.
Gene: Protein-coding gene on chromosome 16 (11,275,639 to 11,276,480, reverse strand). Ensembl gene ENSG00000122304.
Subcellular location: Nucleus; Chromosome
Pathways (Reactome):
Developmental Biology: Replacement of protamines by nucleosomes in the male pronucleus
Gene Ontology:
Molecular function: cadmium ion binding; protein binding; zinc ion binding; DNA binding
Biological process: chromosome organization; nucleus organization; spermatid development; spermatogenesis
Cellular component: nucleus; chromosome; nucleoplasm
Genetic constraint (gnomAD): Loss-of-function variants: 6 observed, 12.12 expected, observed/expected ratio (o/e) 0.5, 90% interval 0.27 to 0.98. The upper end of that interval is the gene's LOEUF score, 0.98, which puts it in group 4 of 6, group 1 being the genes least tolerant of losing a copy. Missense variants: 194 observed, 154.67 expected, observed/expected ratio (o/e) 1.25, 90% interval 1.12 to 1.41. Synonymous variants: 64 observed, 56.92 expected, observed/expected ratio (o/e) 1.12, 90% interval 0.92 to 1.38.
Homologues: Orthologues: chimpanzee PRM2 (86% identical), macaque PRM2 (85% identical), mouse Prm2 (64% identical), rat Prm2 (54% identical), pig PRM2 (51% identical).
Diseases named in the same sentence as PRM2 in open-access papers:
PRM2 is named in the same sentence as 18 diseases in open-access papers, as found by Europe PMC text mining. Sharing a sentence is not in itself a finding about the gene and the disease. The quoted sentences say what the papers report.
infertile (26 papers, 2012 to 2025). "Insufficient PRM-1 and PRM-2 concentrations have been implicated in subfertile or severe infertile condition." (PMID 32960520, 2021). "They showed a significant correlation between reduction ofYBX2 gene expression and low level of PRM2 deficiencyin testicular spermatozoa in infertile men." (PMID 34155862, 2021). "Here we provide for the first time evidence that Prm2 deficiency triggers oxidative stress leading to DNA damage, and thus infertility." (PMID 32727081, 2020). "PRM1 rs2301365 and PRM2 rs1646022 polymorphisms were associated with an elevated risk of male infertility and PRM2 rs2070923 polymorphism had a protective role in infertile men." (PMID 33057064, 2020). "The results showed PRM1 rs2301365 and PRM2 rs1646022 polymorphisms were associated with an elevated risk of male infertility and PRM2 rs2070923 polymorphism had a protective role in infertile men." (PMID 33057064, 2020). "Two mutations of C248T and C67T were identified in PRM2 gene in two different studies in infertile cases with azoospermia." (PMID 25246894, 2012). "Since the ratio between PRM1 and PRM2 is constant in mature sperm (in mice ~60% PRM2), and alterations of this ratio are associated with sperm defects and infertility, we next tested if male mice harboring the Prm2Δc allele display alterations of the PRM1/PRM2 ratio." (PMID 35763544, 2022). "We hypothesized that an aberrant interaction between the newly generated mP2 and the PRM2 precursor expressed from the wildtype allele might lead to interference and be causative for infertility in these males." (PMID 35763544, 2022). "Alterations of the species-specific ratio between PRM1 and PRM2 are associated with infertility." (PMID 35763544, 2022). "PRM2 deficiency can trigger oxidative stress, leading to DNA damage, which leads to infertility." (PMID 34221106, 2021). "Thus, Prm2-deficient testicular sperm appear not only morphologically intact but also functionally capable to overcome infertility of Prm2-/- males using ART." (PMID 32727081, 2020). "Low levels of PRM2 may be associated with morphological abnormalities, initiation of the apoptotic pathway, and decreasing sperm motility in the study using the semen of infertile men36." (PMID 37891374, 2023). "Insufficient protamine incorporation is further indicative of increased retention of histones, as sperm from infertile men exhibited increased histone H2B and reduced Prm1:Prm2." (PMID 39600339, 2024). "Our results provide new insight into the role of Prm2 and its downstream molecular effects on sperm function and present an important contribution to the investigation of new treatment regimens for infertile men with impaired protamination." (PMID 32727081, 2020). "In a study on bulls, the RNA levels of PRM1 were reduced in low-fertility animals, and in humans, PRM1/PRM2 sperm ratios differed between fertile and infertile men." (PMID 33292187, 2020). "Lewiset al. observed that in sperm of infertile men,PRM2 downregulation occurred much more frequentlythan PRM1 deregulation, because PRM2expression was more sensitive to the variation ofregulatory controlling mechanisms than those forPRM1." (PMID 26644857, 2015). "Onthe basis of the studies which showed high PRM1/PRM2 ratios, it has been supposed that a reductionin PRM2 expressions was responsible for aberrantPRM1/PRM2 ratios in infertile males." (PMID 26644857, 2015). "Sperm from infertile men show altered PRM1/PRM2 ratio or undetectable PRM2 in mature sperm, with a PRM1/PRM2 >1 ratio and embryos derived from sperm deficient in PRM2 had their development affected." (PMID 41393904, 2025). "In humans, small changes in the ratio of PRM1 to PRM2 can also lead to infertility." (PMID 38928079, 2024). "Conversely, while Prm2−/− mice are infertile, the heterozygous loss of PRM2 does not lead to subfertility." (PMID 37766963, 2023).
infertile (continued). "Additionally, the infertility of Prm2+/Δc strongly suggests a dominant effect of the deletion, possibly due to an aberrant interaction with another key protein such as transition proteins, PRM1 or H2A.L.2." (PMID 35763544, 2022). "Lack of protamine-2 (PRM2) can lead to severe membrane defects in spermatozoa, resulting in loss of motility and abnormal sperm head morphology and infertility." (PMID 34221106, 2021). "Along thisline, two studies reported complete selective absenceof PRM2 in infertile men." (PMID 26644857, 2015). "Also, the same study reported alterations in the PRM1:PRM2 ratio and higher rates of DNA fragmentation in men with infertility/subfertility antecedents, which decreased the success of in vitro reproduction techniques, such as intracytoplasmic sperm injection (ICSI) and in vitro fertilization (IVF)." (PMID 36381269, 2022). "However, lack of Prm2 causes infertility with severe defects in sperm head morphology and sperm motility." (PMID 27833122, 2016). "In non-human models, haploinsufficiency of Prm1 and Prm2 in mice results in infertility due to reduced motility, chromatin integrity, and morphology." (PMID 39600339, 2024). "However, Prm2-/Δc males did not produce any litters in at least five confirmed matings each and can be considered infertile." (PMID 35763544, 2022). "However, unlike in mice and humans, where another variant of PRM, PRM2, must have a similar ratio as PRM1, and a ratio that deviates at the protein and mRNA levels, will impact infertility." (PMID 35324839, 2022).
male infertility (20 papers, 2012 to 2026). The inability of the male to effect fertilization of an ovum after a specified period of unprotected intercourse. "Mutations in Prm2 and mt-Nd4 have been associated with human male infertility, suggesting their potential as diagnostic markers." (PMID 41602862, 2026). "The biological relevance of these marker genes is underscored by the fact that mutations in Prm2 and mt-Nd4 are known to be associated with human male infertility, highlighting their potential diagnostic value." (PMID 41602862, 2026). "This is also the case in humans, since impaired protamine 1/2 ratio and accumulation of pre‐PRM2 are associated with male infertility." (PMID 37099396, 2023). "Since Prm2+/- male mice are reported to be fertile, these data clearly indicate, that loss of cP2 leads to male infertility in mice." (PMID 35763544, 2022). "This study was performed to investigate the correlation of some single nucleotide polymorphisms of PYGO2, DAZL, PRM1, and PRM2 genes with male infertility in idiopathic cases among the Iranian population." (PMID 36197138, 2022). "Although a distinct pathway has not been found yet, the reduced transcription of postmeiotic genes, including Tnp1, Tnp2, Prm1 and Prm2, in Brwd1-defective testes has been suggested to cause male infertility." (PMID 34473250, 2021). "As for PRM2 rs1646022 polymorphism, the CC genotype was associated with a reduced risk of male infertility (OR 0.69; 95% CI 0.51, 0.94; P = 0.02) in the Caucasian ethnicity and C allele (OR 0.65; 95% CI 0.46, 0.93; P = 0.02) in the mixed ethnicity." (PMID 33057064, 2020). "The association between PRM1 and PRM2 polymorphisms and the risk of male infertility was evaluated using specific search terms in the Web of Science, Cochrane Library, PubMed, and Scopus databases without language restriction until January 28, 2020." (PMID 33057064, 2020). "Based on the results, the C allele and CC genotype of PRM2 rs2070923 polymorphism were associated with the reduced risk of male infertility." (PMID 33057064, 2020). "It has been shown that PRM1 and PRM2 variants are related to male infertility in both humans and animals." (PMID 33057064, 2020). "The aim of the present meta-analysis was to evaluate the association between PRM1 (rs737008 and rs2301365) and PRM2 (rs1646022 and rs2070923) polymorphisms and susceptibility to male infertility." (PMID 33057064, 2020). "The results of meta-regression showed that publication year was a cofounding factor involved in the association between PRM1 rs737008, PRM1 rs2301365, and PRM2 rs1646022 polymorphisms and susceptibility to male infertility." (PMID 33057064, 2020). "Based on the results, the G allele of PRM2 rs1646022 polymorphism was associated with the elevated risk of male infertility." (PMID 33057064, 2020). "Taken together, MS data imply that loss of PRM2 triggers a molecular cascade that initiates described secondary sperm defects, which ultimately result in male infertility." (PMID 32727081, 2020). "They revealed that rs1646022 noticeably decreased the risk of male infertility in the Asian population, because this mutation leads to failure of some key enzymes for cutting and jointing of the PRM2 gene during the protamine translation process." (PMID 30123866, 2018). "Previous studies have shown that rs737008 and rs2301365 in PRM1, and rs1646022 in PRM2, were significantly associated with male infertility." (PMID 28977892, 2017). "Our data showed that rs737008 and rs2301365 in PRM1, and rs1646022 in PRM2, were significantly associated with male infertility and that gene–gene interaction played a role in male infertility." (PMID 28977892, 2017). "Our study showed that rs737008 and rs2301365 in PRM1, and rs1646022 in PRM2, were significantly associated with male infertility and that gene–gene interactions played a role in male infertility." (PMID 28977892, 2017).
male infertility (continued). "Consistently, clinical studies in humans have demonstrated an association of PRM1 and PRM2 variants with male infertility." (PMID 26472740, 2015). "The present meta-analysis including 7350 cases and 6167 controls from 13 case-control studies explored the association between PRM1 and PRM2 polymorphisms and male infertility." (PMID 26472740, 2015). "Firstly, variants of PRM1 and PRM2 are relatively common in male infertility patients, but rare in fertile men." (PMID 26472740, 2015). "A number of molecular epidemiological studies have been conducted to examine the association between PRM1 and PRM2 polymorphisms and male infertility in diverse populations." (PMID 26472740, 2015). "Initially, we focused on the relationship between PRM1 and PRM2 polymorphisms and male infertility risk." (PMID 26472740, 2015). "While looking for reasons for male infertility, it was concluded that the most likely cause is the lowered level of human protamine 2 in sperm." (PMID 22448131, 2012). "The establishment of Prm2−/− mouse strain has unveiled a notable link between Protamine 2 deficiency and male infertility characterized by morphologically impaired and immotile sperm, and a follow-up study suggested a possible molecular mechanism behind described sperm dysfunction." (PMID 39524225, 2024). "Also, variants of PRM1 and PRM2 have been shownto be associated with male infertility and abnormal spermmorphology." (PMID 30644249, 2019). "The findings ofthe present survey are in agreement with the mentionedprevious study, demonstrating the probable relationshipbetween male infertility in patients with tapered headsperms and PRM2 polymorphisms as well as sperm protaminedeficiency, apoptosis rate, and morphology." (PMID 30644249, 2019). "Among them, miRNAs (has-miR-3127-5p and has-miR-3184-5p), lncRNAs (AL356488.2 and AL645608.3) and TFs (NANOG and HEY1) as the key regulatory factors of PRM2, FSCN3 and TEKT2, were predicted significantly associated with male infertility." (PMID 37891374, 2023). "In this study, we tried to find the association of some SNPs of PYGO2, PRM1, PRM2, and DAZL genes with male infertility." (PMID 36197138, 2022). "As in our meta-analysis, there was an elevated risk of male infertility for PRM1 rs2301365 polymorphism only in Caucasians and for PRM2 rs1646022 polymorphism only in Asians." (PMID 33057064, 2020). "A number of reports have verifieddifferent variations in PRM1 and PRM2 sequences(NM_002761.2 and NM_002762.3) in humans with variousassociations with male infertility." (PMID 30644249, 2019). "A meta-analysis evaluated the potential association between male infertility and 6 common SNPs of PRM1 & PRM2 including rs35576928, rs737008, rs35262993, rs2301365, rs1646022, rs2070923." (PMID 30123866, 2018). "This study has evaluated frequency of six previously reported variations in protamine genes cluster consisted of reported mutations in PRM1, PRM2 and TNP2 and their relationship to male infertility in Iranian population." (PMID 25246894, 2012). "Some SNPs such as C248T alteration in the PRM2 gene have reported in some populations which have been important in male infertility." (PMID 25246894, 2012). "Because of the ability of nickel ions to penetrate the blood-testis barrier, to easily bind to protamine 2, and to mediate in production of free radicals, their presence in the testes leads to male infertility." (PMID 22448131, 2012). "A variety of studiesreported a relationship between abnormal PRM1/PRM2 ratios and male infertility." (PMID 26644857, 2015). "According to the literature, spermatogenesisbased disorders in male infertility have a significant relationship with the expression level of some RNA molecules(like DAZ and PRM1/PRM2 ratio) in semen and testicular tissue." (PMID 34155862, 2021). "Recent investigations represented different variations in PRM1, PRM2 and TNP2 gene sequences in human with various relationships to male infertility." (PMID 25246894, 2012).
male infertility (continued). "However, we found that the PRM1 and PRM2 haplotypes GCTGC, TCGCA and TCGCC exhibited significant protective effects against male infertility compared to fertile men, while TCGGA, GCTCC and TCGGC represented significant risk factors for spermatogenesis." (PMID 28977892, 2017). "In conclusion, we found that the PRM1 and PRM2 haplotypes GCTGC, TCGCA and TCGCC exhibited significant protective effects against male infertility as compared to fertile men, except for TCGGA, GCTCC and TCGGC which could represent a significant increased risk of spermatogenesis." (PMID 28977892, 2017).
Azoospermia (11 papers, 2011 to 2024). Absence of any measurable level of sperm,whereby spermatozoa cannot be observed even after centrifugation of the semen pellet. "The expression of genes such as protamine 2 (PRM2) and deleted in azoospermia (DAZ), which can be affected by lifestyle and used as molecular markers in NOA patients, has been evaluated to predict the absence of mature spermatozoa." (PMID 38790168, 2024). "TXNDC2, along with protamine 1 and 2 (PRM1 and PRM2), was significantly decreased in patients with different patterns of NOA compared to OA patients, suggesting that TXNDC2, PRM1, and PRM2 have a robust power to predict sperm retrieval and are correlated with phenotypes of severe azoospermia." (PMID 37174638, 2023). "TXNDC2 (effect size = − 4.25, FDR = 1.44E−15), PRM1 (effect size = − 5.37, FDR = 1.99E−10), PRM2 (effect size = − 5.16, FDR = 3.60E−10), and TNP1 (effect size = − 7.05, FDR = 6.48E−16) were all downregulated in the idiopathic azoospermia dataset." (PMID 34158577, 2021). "This study conduct on23 idiopathic azoospermia men and 5 fertile men as the control group for analyzing the DAZ, RBMY1, USP9Y, protamine-2, SRY, and actin gene expression." (PMID 33349804, 2020). "Detection of DAZ (deleted in azoospermia), DAZL (DAZ-like) and protamine 2 (PRM2) mRNA in testicular samples was shown to be an informative tool for spermatogenesis evaluation." (PMID 23675907, 2013). "The expression levels of germ-cell-specific mRNAs such as protamine 1 (PRM1), protamine 2 (PRM2), deleted in azoospermia (DAZ), and A-kinase anchoring protein 4 (AKAP4) have also been associated with SRR outcomes, with detectable levels linked to higher SRR rates in some studies." (PMID 39767586, 2024). "The regulatory network of TF-miRNA-mRNA and lncRNA-miRNA-mRNA was predicted and revealed that has-miR-3127-5p and has-miR-3184-5p might be the regulator of PRM2、FSCN3 and TEKT2 and play a critical role in azoospermia and TGCT." (PMID 37891374, 2023). "Toconfirm this pathway in human spermatogenesis and test whether abnormality ofthis pathway may contribute to pathogenesis of azoospermia,we compared theexpression profile of CFTR, CREB and the spermatogenic marker protamine-2 innormal human and non-obstructive azoospermia (NOA) testes." (PMID 21625623, 2011).
Teratozoospermia (2 papers, 2015 to 2019). "A polymorphism in the PRM1 promoter (190C.A) is known to increase PRM1 to PRM2 ratio.The aim of our study was to examine the association of SNPsin PRM1 and PRM2 with idiopathic teratozoospermia." (PMID 30644249, 2019). "Tuttelmann and colleagues proposed that 5 SNPs (rs35262993, rs35576928, rs737008, rs1646022 and rs2070923) of PRM1 and PRM2 are associated with mild oligozoospermia (n = 77) or teratozoospermia (n = 88) in a Caucasian population." (PMID 26472740, 2015).
varicocele (2 papers, 2024 to 2025). A condition characterized by the dilated tortuous veins of the spermatic cord with a marked left-sided predominance. "Similarly, elevated protamine-1/protamine-2 ratios have also been observed in varicoceles, which is thought to have downstream consequences impacting chromatin packaging, ultimately affecting the expression of key genes." (PMID 38392299, 2024).
asthenozoospermia (1 paper, 2018). "Among these nine highly prevalent polymorphism areas, the allele frequencies of three SNPs in asthenozoospermia men including 373C>A (r s2070923) and 298G>C (rs1646022) in PRM2 and 139C>A (rs737008) in PRM1 were insignificantly higher than the control group." (PMID 30123866, 2018). "The human PRM1 and PRM2 gene sequences were screened in search of potential mutations in highly prevalent polymorphism regions in asthenozoospermia versus normozoospermia." (PMID 30123866, 2018). "Therefore, this research evaluated the polymorphism of PRM1 and PRM2 in men, diagnosed with asthenozoospermia." (PMID 30123866, 2018).
COVID-19 (1 paper, 2022). A disease caused by infection with severe acute respiratory syndrome coronavirus 2. "At the same time, the expression of the classical marker genes TNP1, PRM1 and PRM2 of sperm were reduced in COVID-19." (PMID 36685935, 2022).